PANO1 (proapoptotic nucleolar protein 1)
Description:
Apoptosis-inducing protein that modulates the tumor suppressor function of CDKN2A/p14ARF. Enhances the stability of CDKN2A/p14ARF protein by protecting it from degradation. May act as a tumor suppressor.
Synonyms: PANO
Tractability: No criterion of Open Targets' tractability assessment is met for any kind of drug.
Gene: Protein-coding gene on chromosome 11 (797,511 to 799,190, forward strand). Ensembl gene ENSG00000288675.
Subcellular location: Nucleus, nucleolus
Gene Ontology:
Biological process: negative regulation of proteasomal ubiquitin-dependent protein catabolic process; positive regulation of apoptotic process; regulation of protein stability
Cellular component: nucleolus
Homologues: Orthologues: chimpanzee PANO1 (97% identical).
Diseases named in the same sentence as PANO1 in open-access papers:
PANO1 is named in the same sentence as 2 diseases in open-access papers, as found by Europe PMC text mining. Sharing a sentence is not in itself a finding about the gene and the disease. The quoted sentences say what the papers report.
COVID-19 (1 paper, 2021). A disease caused by infection with severe acute respiratory syndrome coronavirus 2. "Then, we further investigated the function of OGT to explore the potential mechanism of PANO1 in the risk of COVID-19." (PMID 34290742, 2021). "As genes related to neurological disease and risk genes for COVID-19, OGT, and PANO1 must be considered further." (PMID 34290742, 2021).
neurological disease (1 paper, 2021). "Functional analysis of these genes showed that UQCRH participates in cardiac muscle contraction, PPA2 is closely related to sudden cardiac failure (SCD), and OGT, as the interacting gene partner of PANO1, is associated with neurological disease." (PMID 34290742, 2021).